PAH (phenylalanine hydroxylase)
Diseases named in the same sentence as PAH in open-access papers (continued):
Sharing a sentence is not in itself a finding about the gene and the disease.
phenylketonuria (continued). "Phenylketonuria (PKU), which is caused by mutations in the phenylalanine hydroxylase (PAH) gene, is one of the most common inherited diseases of amino acid metabolism." (PMID 31471952, 2020). "Phenylalanine hydroxylase–deficient (PAH-deficient) phenylketonuria (PKU) is the paradigm for treatable inborn errors of metabolism, motivating development of the first prospective newborn screening programs." (PMID 33055427, 2020). "PHENYLKETONURIA, also known as PKU, is an inborn error of metabolism due to phenylalanine hydroxylase deficiency." (PMID 32605583, 2020). "Phenylketonuria (PKU) is a rare autosomal recessive disorder caused by a defective function of the phenylalanine hydroxylase enzyme leading to an impaired conversion of the amino acid phenylalanine (Phe) to tyrosine." (PMID 32054509, 2020). "Phenylketonuria (PKU) is an inborn error of metabolism caused by the deficiency or insufficiency of the enzyme phenylalanine hydroxylase (PAH), responsible for converting the amino acid phenylalanine (phe) into tyrosine (tyr)." (PMID 32426233, 2020). "Phenylketonuria (PKU) (OMIM 261600) is an autosomal recessive genetic disease caused by insufficient activity of the enzyme phenylalanine hydroxylase, which catalyzes the transformation of phenylalanine (Phe) to tyrosine (Tyr)." (PMID 32520722, 2020). "Phenylketonuria (PKU; McKusick #261600) is a rare autosomal recessive inborn disorder caused by a mutation in the gene encoding phenylalanine hydroxylase (PAH), which is responsible for the transformation of phenylalanine (Phe) into tyrosine." (PMID 32742934, 2020). "The PAH VCEP published functional study guidelines for variants in the phenylalanine hydroxylase (PAH) gene associated with phenylketonuria (PKU)." (PMID 31783775, 2019). "This can be seen, for example, in certain metabolic genetic disorders, such as phenylketonuria (PKU), which is due to a mutation in a single gene (the phenylalanine hydroxylase gene)." (PMID 31354597, 2019). "Phenylketonuria (PKU) is an inherited metabolic disorder caused by a deficiency of the enzyme phenylalanine hydroxylase resulting in neurotoxic accumulation of the amino acid phenylalanine (Phe)." (PMID 30841589, 2019). "Retrospective gene analysis of newborns with clinical phenylketonuria (PKU), identified compound heterozygote phenylalanine hydroxylase (PAH) gene mutations in eight of nine samples (89%)." (PMID 30612563, 2019). "Phenylketonuria (PKU) is a genetic disorder caused by a deficiency of the phenylalanine hydroxylase enzyme." (PMID 31037078, 2019). "In case of decreased or lost phenylalanine hydroxylase activity, a large amount of phenylpyruvic acid is generated, which may lead to phenylketonuria, affecting brain development, causing mental retardation and nervous system symptoms such as microcephaly and convulsions." (PMID 30410553, 2018). "Mutations in the gene encoding phenylalanine hydroxylase (PAH) are associated with various degrees of phenylketonuria (PKU)." (PMID 30050108, 2018). "Phenylketonuria (PKU) is an inborn error of metabolism caused by mutations in the phenylalanine hydroxylase (PAH) gene or by defects in the tetrahydrobiopterin (BH4) synthesis pathway." (PMID 29596327, 2018). "Phenylketonuria (PKU), one of the most common inherited inborn errors of metabolism, is caused by the deficiency of the enzyme phenylalanine hydroxylase (PAH), which catalyzes the conversion of the phenylalanine (Phe) into tyrosine." (PMID 29615849, 2018). "For example, a mutation in the gene coding for the enzyme phenylalanine hydroxylase leads to an inability to properly metabolize the amino acid phenylalanine, resulting in the life-threatening disease phenylketonuria (PKU)." (PMID 28684688, 2017). "Phenylketonuria (PKU) is an inborn error of metabolism that causes mutations in the phenylalanine hydroxylase (PAH) gene." (PMID 29057118, 2017).
phenylketonuria (continued). "Phenylketonuria (PKU) is a genetic metabolic disease in which the decrease or loss of phenylalanine hydroxylase (PAH) activity results in elevated, neurotoxic levels of phenylalanine (Phe)." (PMID 28282402, 2017). "Phenylketonuria (PKU) is a rare inborn syndrome caused by a mutation in a single gene that encodes for the enzyme phenylalanine hydroxylase." (PMID 28383492, 2017). "Phenylketonuria (PKU) is autosomal recessive disorder, caused by mutations in both alleles of the gene for phenylalanine hydroxylase." (PMID 29263844, 2017). "Hyperphenylalaninemia (HPA) can be classified into phenylketonuria (PKU) which is caused by mutations in the phenylalanine hydroxylase (PAH) gene, and BH4 deficiency caused by alterations in genes involved in tetrahydrobiopterin (BH4) biosynthesis pathway." (PMID 28915855, 2017). "The primary defect in the inherited metabolic disease phenylketonuria (PKU) is the disrupted phenylalanine (Phe) metabolism, caused by mutations in the gene encoding for the hepatic enzyme phenylalanine hydroxylase, which normally converts Phe to tyrosine." (PMID 27102170, 2016). "Phenylketonuria (PKU) is an autosomal recessive disorder caused by the deficiency of phenylalanine hydroxylase that catalyzes the conversion of phenylalanine to tyrosine, using tetrahydrobiopterin (BH4) as coenzyme." (PMID 25757997, 2015). "Phenylketonuria (PKU) is an autosomal recessive disease which results from mutations in the phenylalanine hydroxylase (PAH) gene." (PMID 26413448, 2015). "Phenylketonuria (PKU) is caused by the deficiency of phenylalanine hydroxylase which is required to essential amino acids, phenylalanine (phe), to tyrosine." (PMID 25415675, 2014). "Phenylketonuria (PKU OMIM 261600) is an autosomal recessive disorder caused by mutations in the phenylalanine hydroxylase (PAH) gene." (PMID 25375236, 2014). "Phenylketonuria (PKU; McKusick 2610600) is an inherited metabolic disease caused by a deficiency of the enzyme phenylalanine hydroxylase, which is necessary to convert phenylalanine to tyrosine." (PMID 22447154, 2012). "Phenylketonuria (PKU) (OMIM 221600) is inborn error of the metabolism resulting from a deficiency of phenylalanine hydroxylase (PAH)." (PMID 20478016, 2010). "Phenylketonuria (PKU; OMIM #261600) is a genetic disorder resulting from a deficiency in phenylalanine hydroxylase, leading to elevated levels of phenylalanine in the blood." (PMID 41515262, 2026). "Individuals with phenylketonuria (PKU), caused by different variants of the phenylalanine hydroxylase gene, need to restrict their intake of phenylalanine." (PMID 42070971, 2026). "In chromosome 12q23.2, the PAH gene is located, which codes for the PAH enzyme involved in the metabolic pathway of phenylketonuria." (PMID 41158521, 2025). "One of the most well‐known disorders is phenylketonuria (PKU), which results from a deficiency in the enzyme phenylalanine hydroxylase." (PMID 40365712, 2025). "Phenylketonuria (PKU, OMIM 261600) is an autosomal recessive disorder caused by a deficiency of the phenylalanine hydroxylase (PAH) enzyme." (PMID 40871680, 2025). "Phenylketonuria (PKU; OMIM 261600) is an inborn error of metabolism caused by mutations in the phenylalanine hydroxylase (PAH) gene." (PMID 40136633, 2025). "Phenylketonuria (PKU; OMIM # 261600) is an autosomal recessive disorder characterized by the deficiency of phenylalanine hydroxylase (PAH; EC 1.14.16.1), which converts phenylalanine (Phe) into tyrosine (Tyr)." (PMID 40751258, 2025). "Phenylketonuria (PKU; OMIM #261600) is an inborn error of metabolism (IEM) caused by pathogenic variants in the gene encoding the enzyme phenylalanine hydroxylase (PAH) with a global prevalence estimated at approximately 1:23,930 live births." (PMID 41465241, 2025).
phenylketonuria (continued). "Phenylketonuria (PKU, ORPHA79254, MIM 261600) is an inherited metabolic disorder caused by mutations in the Phenylalanine Hydroxylase (PAH) gene, coding the enzyme responsible for the metabolization of Phenylalanine (Phe) into Tyrosine (Tyr)." (PMID 41295339, 2025). "Phenylketonuria (PKU) is a rare, metabolic disorder, caused by a deficiency of the enzyme phenylalanine hydroxylase (PAH) that catalyses the hydroxylation of phenylalanine (Phe) to tyrosine." (PMID 39164733, 2024). "Phenylketonuria (PKU, OMIM #261600) is an autosomal recessive deficiency of phenylalanine hydroxylase (PAH), an enzyme catalyzing the conversion of phenylalanine (Phe) to tyrosine (Tyr)." (PMID 39022300, 2024). "Phenylketonuria (PKU) is a treatable hereditary metabolic cause of intellectual disability linked to a defect in the phenylalanine-hydroxylase (PAH) enzyme that converts phenylalanine (Phe) into tyrosine (Tyr), which leads to Phe accumulation in the blood and body tissues." (PMID 38673463, 2024). "Phenylketonuria (PKU) is an autosomal, recessive, inherited metabolic disorder caused by phenylalanine hydroxylase (PAH) gene mutations." (PMID 38794682, 2024). "Phenylketonuria (PKU; OMIM 261600) is a rare autosomal recessive genetic disorder triggered by mutations in the phenylalanine hydroxylase (PAH) gene, leading to reduced catalytic activity and affecting the breakdown of phenylalanine (Phe)." (PMID 38542680, 2024). "Phenylketonuria (PKU) is the most common inherited amino acid disorder, due to a deficiency of Phenylalanine Hydroxylase (PAH), which converts Phenylalanine (Phe) into Tyrosine (Tyr)." (PMID 37894204, 2023). "The main type of HPA is phenylketonuria (PKU), an autosomal recessive disease caused by variants of PAH, the gene encoding phenylalanine hydroxylase." (PMID 37237386, 2023). "Phenylketonuria (PKU; OMIM 261600) is the most prevalent IEM caused by pathogenic variants in the phenylalanine hydroxylase gene (PAH, OMIM * 612349), which catalyzes the hydroxylation of phenylalanine (Phe) to tyrosine (Tyr)." (PMID 36768810, 2023). "Phenylketonuria (PKU) is a common, congenital, autosomal recessive, metabolic disorder caused by Phenylalanine hydroxylase (PAH) variants." (PMID 37098607, 2023). "Phenylketonuria (PKU) is an autosomal recessive disease caused by deficiencies in phenylalanine metabolism, due to mutations in the phenylalanine hydroxylase (PAH) gene." (PMID 36678793, 2023). "Phenylketonuria (PKU), an autosomal recessive disorder caused by pathogenic variants in the phenylalanine hydroxylase (PAH) gene, results in the accumulation of blood phenylalanine (Phe) to neurotoxic levels." (PMID 37301931, 2023). "Hyperphenylalaninemia (HPA), which includes phenylketonuria (PKU), is a genetic autosomal recessive disorder arising from a deficiency in the enzyme named phenylalanine hydroxylase (PAH)." (PMID 38136067, 2023). "Hyperphenylalaninemia (HPA), including phenylketonuria (PKU), is a class of diseases caused by the impairment of the enzyme Phenylalanine hydroxylase (PAH), both for mutations in the corresponding PAH gene encoding the enzyme and for deficiency of the BH4 cofactor." (PMID 37101826, 2023). "The most common example of IEM is tetrahydrobiopterin (BH4), the cofactor for phenylalanine hydroxylase, which is defective in patients with phenylketonuria (PKU)." (PMID 36982893, 2023). "Phenylketonuria (PKU) is a rare metabolic disease caused by variations in a human gene, PAH, encoding phenylalanine hydroxylase (PAH), and the enzyme converting the essential amino acid phenylalanine into tyrosine." (PMID 35562892, 2022). "Phenylketonuria (PKU) is an autosomal-recessive inborn error of phenylalanine (Phe) catabolism, caused by the deficiency of phenylalanine hydroxylase." (PMID 35681715, 2022).
phenylketonuria (continued). "As an example, phenylketonuria (PKU) is the most prevalent IEM and is an autosomal recessive disorder caused by the loss of phenylalanine hydroxylase (PAH) activity, the first step in phenylalanine catabolism." (PMID 35736461, 2022). "Phenylketonuria (PKU) is caused by a specific mutation of the phenylalanine hydroxylase (PAH) gene." (PMID 39872976, 2022). "Phenylketonuria (PKU, OMIM 261600) is an inherited metabolic disorder caused by mutations in the phenylalanine hydroxylase (PAH) enzyme that impairs phenylalanine (Phe) metabolism, leading to high blood and brain Phe concentrations." (PMID 35267995, 2022). "Phenylketonuria (PKU) is the most prevalent inherited metabolic disorder and is characterized by mutations in the phenylalanine hydroxylase (PAH) gene that encodes the PAH enzyme (EC1.14.16.1)." (PMID 35987969, 2022). "Phenylalanine hydroxylase deficiency (PAHD, MIM#261,600) is an autosomal recessive metabolic disorder caused by variants in the gene encoding the enzyme phenylalanine hydroxylase (PAH; EC 1.14.16.1)." (PMID 36104584, 2022). "Phenylketonuria (PKU; OMIM 261600) is an inborn error of metabolism (IEM) caused by a deficiency of the phenylalanine hydroxylase (PAH) enzyme responsible for the phenylalanine (Phe) to tyrosine (Tyr) conversion." (PMID 33742102, 2021). "Phenylketonuria (PKU; OMIM 261600) is the most common IMD of amino acid metabolism (1:10,000 newborns) and is caused by mutations in the PAH gene, encoding phenylalanine hydroxylase (hPAH; EC 1.14.16.1)." (PMID 33808760, 2021). "Phenylketonuria (PKU; McKusick #261600) is a rare autosomal recessive inborn error of phenylalanine (Phe) metabolism, caused by a deficiency in the hepatic enzyme phenylalanine hydroxylase (PAH)." (PMID 33407655, 2021). "Phenylketonuria (PKU) can be treated and caused by deficiency of phenylalanine hydroxylase enzyme in newborn babies." (PMID 33467753, 2021). "The deficiency of the enzyme phenylalanine-4-hydroxylase (PAH), which catalyzes the conversion of the essential amino acid phenylalanine (Phe) to tyrosine, results in phenylketonuria (PKU, OMIM 261600)." (PMID 34441968, 2021). "Phenylketonuria (PKU) and hyperphenylalaninemia (HPA) are autosomal recessive disorders characterized by the deficiency of hepatic phenylalanine hydroxylase (PAH)." (PMID 33803550, 2021). "Phenylketonuria is a recessive genetic disorder of amino-acid metabolism, where impaired phenylalanine hydroxylase function leads to the accumulation of neurotoxic phenylalanine levels in the brain." (PMID 35082602, 2021). "Phenylketonuria (PKU), or phenylalanine hydroxylase deficiency (PAH deficiency), is an autosomal recessive disorder of phenylalanine (Phe) metabolism caused by a deficiency of the enzyme phenylalanine hydroxylase (PAH)." (PMID 34444879, 2021). "Phenylketonuria (PKU) is a rare autosomal recessive inborn error of phenylalanine (Phe) metabolism, caused by a mutation in the phenylalanine hydroxylase gene (PAH, cDNA sequence, GenBank U49897) encoding the enzyme L-phenylalanine hydroxylase (EC 1.14.16.1)." (PMID 34204602, 2021). "Phenylketonuria (PKU; MIM# 261600) is the most common inherited disorder of amino acid metabolism, which is caused by mutations in the phenylalanine hydroxylase (PAH) gene." (PMID 34900593, 2021). "Phenylketonuria (PKU) is a rare metabolic disorder caused by a deficiency of phenylalanine hydroxylase (PAH), the enzyme that catalyses the hydroxylation of phenylalanine to tyrosine, and which leads to irreversible intellectual impairment in untreated children." (PMID 32899129, 2020). "Phenylketonuria (PKU), which is characterized by a deficiency of phenylalanine hydroxylase activity, is an autosomal recessive disorder of phenylalanine (Phe) metabolism." (PMID 32703178, 2020). "Phenylketonuria (PKU), which is characterized by a deficiency of phenylalanine hydroxylase (PAH) activity, is an autosomal recessive disorder of phenylalanine (Phe) metabolism." (PMID 32703178, 2020).
phenylketonuria (continued). "Phenylketonuria (PKU) is one of the most prevalent autosomal recessive disorders of amino acid metabolism, resulting from a severe deficiency in the activity of the catalytic enzyme phenylalanine hydroxylase (PAH)." (PMID 31471952, 2020). "A well-known example of a disorder associated with hyperphenylalaninemia is phenylketonuria (PKU; McKusick 261600), caused by a deficiency of the enzyme phenylalanine hydroxylase." (PMID 32599819, 2020). "Phenylketonuria (PKU), due to phenylalanine hydroxylase deficiency, leads to accumulation of phenylalanine and irreversible brain damage if untreated." (PMID 32899700, 2020). "Chemically modified PAL has been used as a therapy for phenylketonuria (PKU), which is an inborn disorder of phenylalanine metabolism caused by deficiency of phenylalanine hydroxylase (PAH), causing cognitive development loss and mental retardation as a result of hyperphenylalaninemia." (PMID 31581382, 2020). "Phenylketonuria (PKU; MIM 261600) is an autosomal recessive disorder caused by the deficiency of phenylalanine hydroxylase (PAH, EC 1.14.16.1), the hepatic enzyme that converts phenylalanine (Phe) to tyrosine (Tyr), using tetrahydrobiopterin (BH4) as coenzyme." (PMID 32326614, 2020). "Phenylketonuria (PKU) is an inherited metabolic disorder characterized by reduced activity of phenylalanine hydroxylase resulting in elevated blood phenylalanine (Phe) concentration." (PMID 32450880, 2020). "Phenylketonuria (PKU; OMIM 261600) is an inborn error of phenylalanine (Phe) metabolism caused by an inherited deficiency in L-phenylalanine-4-hydroxylase (PAH; EC 1.14.16.1) activity, leading to elevated levels of Phe in body fluids." (PMID 31284588, 2019). "Phenylketonuria (PKU, OMIM 261600) is an autosomal recessive disorder defined by a deficiency of phenylalanine hydroxylase (PAH, EC 1.14.16.1) resulting in a complete or partial inability to convert phenylalanine (Phe) into tyrosine." (PMID 31052331, 2019). "Phenylketonuria (PKU) is an autosomal recessive genetic disorder in which the enzyme, phenylalanine hydroxylase (PAH), produced in the liver, is deficient." (PMID 31741827, 2019). "Phenylketonuria (PKU) is, in 98–99% of cases, due to an inherited deficiency in the enzyme phenylalanine hydroxylase (PAH), which results in elevated levels of the essential amino acid phenylalanine (Phe) and reduced levels of tyrosine." (PMID 31331350, 2019). "Phenylketonuria (PKU) is an autosomal-recessive inborn error of phenylalanine (Phe) metabolism, caused by the deficiency of the enzyme phenylalanine hydroxylase (PAH)." (PMID 31492166, 2019). "In phenylketonuria (PKU; McKusick 261600), mutations in the gene encoding for the hepatic enzyme phenylalanine hydroxylase, that normally converts phenylalanine (Phe) into tyrosine, result in toxic accumulation of Phe in blood and brain." (PMID 31546852, 2019). "Of highest frequency was the rs5030858 variant in the PAH gene (MIM#612349; gnomAD NFE AF = 0.0015, p = 7.9 × 10–4), a well‐established and one of the most frequent pathogenic variant for phenylketonuria." (PMID 31482689, 2019). "Phenylalanine hydroxylase (PAH) deficiency is responsible for most cases of phenylketonuria (PKU)." (PMID 30668579, 2019). "Phenylketonuria (PKU) is an inherited metabolic disease characterized by abnormally high concentrations of the essential amino acid L-phenylalanine (Phe) in blood plasma caused by reduced activity of phenylalanine hydroxylase (PAH)." (PMID 31105574, 2019). "Pathogenic mutations in the PAH and PTS genes were detected in four and one phenylketonuria cases, respectively." (PMID 29731766, 2018). "Phenylketonuria (PKU), one of the most common inherited diseases of amino acid metabolism, is caused by mutations in the phenylalanine hydroxylase (PAH) gene." (PMID 29684050, 2018).